LRP5 (LDL receptor related protein 5)
Diseases named in the same sentence as LRP5 in open-access papers (continued):
Sharing a sentence is not in itself a finding about the gene and the disease.
tumor (continued). "Or by overexpressing the dominant-negative, soluble LRP5 (sLRP5) can reverse epithelial-mesenchymal transition of tumor cells by blocking Wnt signaling 20-22." (PMID 38706907, 2024). "OCY coinjection further reduced tumor-driven osteolysis and achieved tumor-suppressive activity through an Lrp5-mediated Wnt signaling pathway." (PMID 38685911, 2023). "Paradoxically, however, the activation of Wnt signaling by the overexpression of Lrp5, a Wnt co-receptor, and β-catenin in osteocytes, generated osteocyte-derived tumor-suppressive CM." (PMID 36810561, 2023). "MUFAs amplify Wnt signaling via stabilization of β-catenin and LRP5/6 in rodent hepatic stellate cells and tumor-initiating cells." (PMID 36817228, 2023). "For instance, the systemic administration of Lrp5-overexpressing CM reduced the weight of mammary tumors and the size of tumor-invaded areas in the lung." (PMID 36810561, 2023). "Co-injection of OCY into the brain exhibited tumor-suppressing capability through Lrp5, IL1ra, and β-catenin upregulation in brain metastases that occur from advanced breast cancer." (PMID 38685911, 2023). "Of note, the activation of Lrp5-mediated Wnt signaling is also reported to convert bone-resorbing osteoclasts into bone-protective, tumor-suppressive cells." (PMID 34976221, 2022). "Lastly, we observed herein that tumor-suppressive secretomes can be induced from tumor cells by the overexpression of Lrp5, MSN, and OPN." (PMID 34976221, 2022). "We next examined the suppressive effect of Lrp5 CM on the tumor invasion in vivo and tumor growth ex vivo." (PMID 34976221, 2022). "We have observed the anti-tumor action of Lrp5 CM, demonstrating that osteoblasts can be converted into iTSCs." (PMID 34976221, 2022). "The results of this study indicate the differential role of Lrp5 in CMs as extracellular proteins and tumor cells as intracellular proteins." (PMID 34976221, 2022). "Of note, the level of TGFβ was downregulated in both Lrp5-overexpressing osteoblasts and Lrp5 CM-treated tumor cells." (PMID 34976221, 2022). "To evaluate the effect of Lrp5 CM on the apoptosis induction of tumor cells, we conducted a protein antibody array analysis." (PMID 34976221, 2022). "Collectively, this study showed that osteoblasts can be converted into iTSCs and Lrp5 CM became an anti-tumor and bone-protective agent." (PMID 34976221, 2022). "These parameters, derived from microCT images, together with the H&E-stained histological sections demonstrated the reduction in the tumor-invaded area by the administration of Lrp5 CM." (PMID 34976221, 2022). "Although the tumour weight in LRP5 activation group was a little heavier than that in the control group after the treatment of cisplatin, this difference was not statistically significant and needs further investigation." (PMID 34997691, 2022). "Consistently, in the mouse model of tumor-driven osteolysis microCT imaging revealed that bone mineral density of the cortical bone in the proximal tibia was elevated in the Lrp5 CM group." (PMID 34976221, 2022). "Similar anti-tumor capability was observed in MSCs generated by overexpressing LRP5, β-catenin, Snail, or Akt." (PMID 35994202, 2022). "It is responsible for regulating tumor cell phenotypes via activating the Wnt signaling through upregulating LRP5." (PMID 36034210, 2022). "Loss of APC in intestinal cancer cells or loss of PTEN in melanoma cells has also been shown to induce DKK2 expression, which coordinates tumor immune evasion via LRP5 and suppression of STAT5 signaling." (PMID 35204808, 2022). "The overexpression of Lrp5 in osteoblasts induced the tumor-suppressive secretome, and its partial silencing reversed the action." (PMID 34976221, 2022). "Although its mechanism of action on osteoblasts and MM cells remains uncertain, this oligopeptide sequesters DKK1 from LRP5/6 and reduces tumor cell growth, providing an option for managing tumor burden in MM." (PMID 35355709, 2022).
tumor (continued). "This study presented the tumor-suppressing capability of osteoblasts by the overexpression of Lrp5, as well as β-catenin and the treatment with BML284." (PMID 34976221, 2022). "Its elevation in tumor cells promoted their tumorigenic behaviors, whereas its upregulation in Lrp5-overexpressing osteoblasts contributed to strengthening tumor-suppressive capabilities." (PMID 34976221, 2022). "Consistently, we observed the anti-tumor effects of Lrp5 CM in the lung using GFP-labeled MDA-MB-231 cells that were inoculated as an i.v. injection from the tail vein of NSG female mice." (PMID 34976221, 2022). "Collectively, these results show that activation of LRP5 exerts a tumour‐promoting role in the development of CRC, both in vivo and in vitro." (PMID 34997691, 2022). "This study presented that loading-driven tumor suppression was mediated by both Lrp5-independent and Lrp5-dependent mechanisms." (PMID 33450808, 2021). "While two Wnt coreceptors, Lrp5 and Lrp6, are known to be involved in bone homeostasis, they played different roles in tumor progression in our study." (PMID 34230453, 2021). "The result revealed that Akt-, Lrp5-, β-catenin- and Snail-overexpressing MSCs and their CMs significantly inhibited the growth of 4T1.2 tumor spheroids." (PMID 33859739, 2021). "For instance, it is well known that the activation of Wnt signaling in tumor cells by the overexpression of β-catenin or Lrp5, or the application of a pharmacological Wnt activator, promotes tumor progression." (PMID 34830748, 2021). "The tumor-promoting genes (Lrp5, MMP9, Runx2 and Snail) in EO771 cells were decreased by treating with Snail-overexpressing MSC CMs and the effect was reversed by silencing Snail." (PMID 33859739, 2021). "Although lipoprotein receptor-related protein 5 (Lrp5) in osteocytes is necessary to induce loading-driven bone formation, loading-driven tumor suppression is regulated by Lrp5-dependent and independent mechanisms." (PMID 33450808, 2021). "Lrp5 was overexpressed in this study since we previously observed that osteocytes with a higher expression level of Lrp5 were more potent to suppress tumor progression." (PMID 33802279, 2021). "In the mice model, the co-injection of Lrp5- and/or IL1ra-overexpressing osteocytes induced a significant reduction in the tumor growth in the brain and maintained superior activity scores and brain damage scores." (PMID 33802279, 2021). "We showed that the anti-tumor effects can be induced not only by the overexpression of β-catenin and Lrp5, a Wnt co-receptor, but also by the administration of the tumor-promoting chemical compound, BML284." (PMID 34373756, 2021). "Paradoxically, Lrp5 and β-catenin are considered tumor-promoting genes, and much of the research efforts are directed to inhibit Wnt signaling." (PMID 33802279, 2021). "Most notably, extracellular histone H4 was elevated in osteocyte-derived CM by overexpressing Lrp5, β-catenin, and IL1ra, and the recombinant histone H4 acted as an atypical tumor suppressor." (PMID 33802279, 2021). "The Lrp5-dependent mechanism was evident since Lrp5-overexpressing osteocytes inhibited the growth of tumor spheroids and Lrp5-silenced osteocytes upregulated tumorigenic genes such as Runx2, MMP9, Snail, and TGFβ." (PMID 33450808, 2021). "Hsp90ab1 reduced the scratch-based migration and downregulated tumor-promoting genes Lrp5, MMP9, Runx2 and Snail in 4T1.2 cells." (PMID 33859739, 2021). "To our surprise, however, we have also shown that the conditioned medium, collected from Lrp5-overexpressing osteocytes and MSCs, can suppress tumor growth." (PMID 34373756, 2021). "We have presented herein that osteocytes and their CM were capable of inhibiting the progression of tumors in the mammary fat pad, tibia, and brain, and their anti-tumor capability was enhanced by the overexpression of Lrp5, β-catenin, and IL1ra." (PMID 33802279, 2021).
tumor (continued). "The next step was the determination of the potential downstream effector, which links loading-driven regulation of the dopamine-Lrp5 axis to tumor-promoting genes such as Snail, MMP9, and Runx2." (PMID 34031366, 2021). "In this study, we examined the potential involvement of Lrp5 in osteocytes in tumor suppression at a locally loaded site of the tibia as well as at a remote non-loaded site of the mammary fat pad." (PMID 33450808, 2021). "Collectively, this study identified Lrp5-dependent and independent mechanisms for tumor suppression." (PMID 33450808, 2021). "To further evaluate the role of Lrp5 in tumor-osteocyte interactions in vitro, we employed Lrp5 plasmids and siRNA." (PMID 33450808, 2021). "The results herein supported that both Lrp5-dependent and independent mechanisms are present in loading-driven tumor suppression." (PMID 33450808, 2021). "This anti-tumor capability was also observed in MSCs that overexpressed varying protumorigenic genes such as β-catenin, Lrp5, snail and Akt." (PMID 34373756, 2021). "In this study, we overexpressed Lrp5 and β-catenin in osteocytes and aimed to enhance their innate anti-tumor capability." (PMID 33802279, 2021). "In conclusion, we observed Lrp5-dependent and independent mechanisms for loading-driven tumor suppression." (PMID 33450808, 2021). "Although Lrp5 is indispensable for loading-driven bone formation, its downregulation was critical to tumor suppression." (PMID 34031366, 2021). "Using three tumor cells (MDA-MB-231, 4T1.2 and EO771) and two normal cells (MSCs and MLO-A5 osteocytes), we determined tumor selectivity for Lrp5 CM, Akt CM, Hsp90ab1, Calr and Ppib." (PMID 33859739, 2021). "In response to the loading-driven elevation of dopamine, we evaluated the expression of Lrp5 and downstream effector genes in tumor cells, including tumor-promoting cytokines and oncogenic genes such as Src, Snail, MMP9, Runx2, and TGFβ." (PMID 34031366, 2021). "We thus far showed that dopamine and FP can act as tumor suppressors by blocking Lrp5-mediated Wnt signaling." (PMID 34031366, 2021). "The result thus indicated that the combined overexpression of IL1ra and Lrp5 further enhanced the osteocyte-driven anti-tumor effect." (PMID 33802279, 2021). "The co-culturing of tumor spheroids with Lrp5-overexpressing osteocyte spheroids shrank tumor spheroids, and their CM downregulated MMP9, Runx2, TGFβ, and Snail." (PMID 33450808, 2021). "The main aim of this study was to identify the role of Lrp5 in inducing loading-driven suppression of tumor progression." (PMID 33450808, 2021). "This study has examined so far the role of β-catenin and BML284 in generating iTS CM from tumor cells as well as non-tumor cells, whereas our previous study showed the same role of Lrp5, a Wnt co-receptor, in producing anti-tumor CM from osteocytes and MSCs." (PMID 34373756, 2021). "Collectively, the result showed that the enhancement of the anti-tumor capability by the overexpression of Lrp5 depended on the type of cells." (PMID 33802279, 2021). "In this study, we found that osteocytes and their conditioned medium (CM) presented the tumor-suppressing capability, and the overexpression of Lrp5, IL1ra, and β-catenin enhanced their anti-tumor actions." (PMID 33802279, 2021). "When a similar approach was implemented in osteocytes, we observed that overexpression of Lrp5, a co-receptor of Wnt signaling, rendered the otherwise naïve osteocytes tumor-suppressive." (PMID 33859739, 2021). "Loading-driven dopamine downregulated Lrp5 in 4T1Br brain-metastasized tumor cells via dopamine receptor D1, followed by a reduction in CCN4, an oncogene inducible by Wnt signaling." (PMID 34031366, 2021). "Osteocytes exhibited elevated Lrp5 expression in response to tumor cells, implying that osteocytes protect bone through canonical Wnt signaling." (PMID 34230453, 2021).
tumor (continued). "Since Lrp5-mediated Wnt signaling can promote tumorigenesis and tumor progression, the tumor-suppressing role of Lrp5 in osteocytes indicates that osteocytes and tumor cells use Lrp5 signaling in distinct and opposing ways." (PMID 33450808, 2021). "In tumor-osteocyte interactions, in which bone formation is promoted by Wnt signaling, we reported that the overexpression of β-catenin and Lrp5, a Wnt co-receptor, granted osteocytes anti-tumor capabilities." (PMID 34373756, 2021). "Taken together, the results reinforced the anti-tumor action of osteocytes and revealed that besides the overexpression of Lrp5 or β-catenin, the anti-tumor effect was also enhanced by the overexpression of IL1ra." (PMID 33802279, 2021). "We employed mice with osteocyte-selective deletion of Lrp5 and evaluated the Lrp5-dependent and independent mechanisms involved in loading-driven tumor suppression." (PMID 33450808, 2021). "Taken together, the in vitro analysis revealed that osteocyte-derived CM presented the tumor-suppressing capability and the anti-tumor action was enhanced by Lrp5 overexpression." (PMID 33802279, 2021). "We also observed that Lrp5-overexpressing mesenchymal stem cells presented the tumor-suppressing capability." (PMID 33802279, 2021). "Having shown Lrp5’s antitumor capability in osteocytes, we next examined the effect of Lrp5 deletion in osteocytes on tumor progression in the tibia in conditional knockout mice." (PMID 34230453, 2021). "In generating enhanced tumor-suppressing CM, the overexpression of Lrp5 and β-catenin in Wnt signaling, as well as IL1ra in inflammatory signaling was examined." (PMID 33802279, 2021). "In the C57BL/6 mouse model, the co-injection of Lrp5-overexpressing MSCs to the mammary fat pad significantly reduced the tumor size driven by EO771 cells." (PMID 33859739, 2021). "Conversely, RNA interference with Lrp5 siRNA in osteocytes reversed the responses in tumor cells with a decrease in chemerin and an increase in nexin." (PMID 33450808, 2021). "In the Lrp5-independent mechanism, it is possible that besides dopamine and cholesterol, other neurotransmitters and metabolites are also involved as systemic tumor-regulating agents in the serum and urine." (PMID 33450808, 2021). "While Lrp5 in tumor cells acts as a tumor promoter in Wnt /β-catenin signaling that is considered a therapeutic target, the result in this study indicates that Lrp5 in osteocytes serves as a tumor suppressor." (PMID 33450808, 2021). "By contrast, Lrp5-silenced osteocyte-derived CM lost the ability to inhibit cell proliferation and invasion, as well as the growth of tumor spheroids." (PMID 34230453, 2021). "We found that overexpressing Lrp5 and constitutively activating β-catenin strengthened this tumor-suppressive capability." (PMID 34230453, 2021). "The highest tumor selectivity was obtained with Lrp5 CM, in which the MTT-based viability of A5 osteocytes was stimulated." (PMID 33859739, 2021). "So far, we have presented evidence of the anti-tumor capability of MSC CMs by the overexpression of Lrp5 or β-catenin." (PMID 33859739, 2021). "This study showed that MSCs were able to gain a tumor-suppressing capability by overexpressing Lrp5, β-catenin, Snail or Akt." (PMID 33859739, 2021). "Using clinically relevant murine tumor models, studies have examined anti-tumor immune responses by blocking Fzd-LRP5/6 signaling." (PMID 32132993, 2020). "To characterize the mechanism of VHH-mediated cell death, we investigated the possibility that blocking LRP5/6-mediated Wnt signaling depletes the self-renewing tumor cell pool by promoting their collective differentiation." (PMID 30664649, 2019). "On the other hand, specific ablation of LRP5 and LRP6 in DCs is associated with delayed tumor progression and enhanced host anti-tumor immunity." (PMID 31684152, 2019). "This suppressed antitumor immunity was explored via DC-specific LRP5/6 deletions in a murine tumor model." (PMID 31167446, 2019).
tumor (continued). "We next examined the tumor formation and Wnt activity following siRNA knockdown of LRP5, LRP6, and β-catenin." (PMID 31881970, 2019). "Recently, we discovered multiple β-catenin independent functions of LRP5/6 in tumor cells and in the diseased heart." (PMID 31881970, 2019). "In conclusion, anti-LRP5/6P3 VHHs effectively target Wnt-dependent tumorigenic organoids by removing an essential pathway for renewal of stem-like tumor cells and promoting their terminal differentiation." (PMID 30664649, 2019). "Both LRP5 and -6 are implicated in mediating Wnt/β-catenin signaling; however, due to the overwhelming role of LRP5 in tumor progression and bone biology, we targeted this gene to define its role in PCa-associated skeletal metastasis 35,36." (PMID 24403228, 2013). "Using our well established xenograft model of PCa, LRP5 knockdown resulted in the development of tumors of a significantly smaller volume, effects which were efficiently maintained for 10 weeks post tumor cell inoculation." (PMID 24403228, 2013). "We have previously shown that Lrp5 is necessary for tumor development in response to Wnt1, despite the co-expression of functional Lrp6 in basal mammary epithelial cells." (PMID 21541292, 2011). "If Lrp5 expression is required to close a paracrine Wnt1-signaling loop that determines cell survival and tumor initiating activity, then Lrp5-positive cells should include most of the tumor stem cells." (PMID 21541292, 2011). "Wnt signaling (via Lrp5 and Wnt1) is therefore necessary and sufficient for cell growth and tumor maintenance." (PMID 21541292, 2011). "Flow cytometric analysis showed the acquisition of low levels of cell surface Lrp5 by a luminal subpopulation, and indeed all the tumor stem cell activity co-purified with the Lrp5-positive cell population." (PMID 21541292, 2011). "Previously, we showed that Lrp5 null mammary glands, though grossly normal (albeit developmentally delayed), were remarkably resistant to Wnt1-induced tumor development." (PMID 19672307, 2009). "This study demonstrates that osteocyte-derived conditioned medium, when LRP5 is overexpressed, not only directly restrains tumor cell aggressiveness but also reprograms the “soil” of the bone microenvironment, thereby achieving multi-faceted therapeutic benefits." (PMID 41596426, 2026). "In summary, our data demonstrate that LRP5-overexpressing osteocyte-derived CM exerts anti-tumor and bone-protective effects in vivo, and that LIMA1 and MYO5B may be relevant factors contributing to these actions within the bone microenvironment." (PMID 41596426, 2026). "Collectively, these findings indicate that LIMA1 functions as a downstream effector of the LRP5/Wnt signaling axis in mediating the anti-tumor actions of LRP5-overexpressing osteocyte-derived CM, and that its knockdown substantially attenuates these inhibitory effects." (PMID 41596426, 2026). "This immunostimulatory pattern was markedly reduced when LIMA1 was knocked down, suggesting that LIMA1 may contribute to the pro-inflammatory, anti-tumor immune microenvironment induced by LRP5-overexpressing osteocyte-derived CM." (PMID 41596426, 2026). "LRP5 in osteocytes plays a critical role in tumor suppression." (PMID 41596426, 2026). "While DKKs are known to bind LRP5/6 and modulate Wnt signaling, recent studies have suggested that DKKs may have broader functions in other contexts, including tumor progression and AD." (PMID 41202125, 2025). "LRP5 dysregulation is known to increase tumor cell proliferation in various cancers." (PMID 40940800, 2025). "Moreover, LRP5 is overexpressed in and regulates tumor growth in triple-negative breast cancer by regulating STK-40 expression, another potential therapeutic target in breast cancer." (PMID 40940800, 2025). "Although overexpression of Wnt proteins LRP5 and β-catenin alone could transform MSCs into iTS cells with tumor-suppressive CM, co-treatment did not enhance ES effects." (PMID 39940798, 2025).